NECTIN2 (nectin cell adhesion molecule 2)
Description:
Modulator of T-cell signaling. Can be either a costimulator of T-cell function, or a coinhibitor, depending on the receptor it binds to. Upon binding to CD226, stimulates T-cell proliferation and cytokine production, including that of IL2, IL5, IL10, IL13, and IFNG. Upon interaction with PVRIG, inhibits T-cell proliferation. These interactions are competitive. Probable cell adhesion protein. (Microbial infection) Acts as a receptor for herpes simplex virus 1 (HHV-1) mutant Rid1, herpes simplex virus 1 (HHV-2) and pseudorabies virus (PRV).
Synonyms: HveB; CD112; PRR2; PVRL2; PVRR2; Nectin-2
Tractability: Antibody: its Gene Ontology location is reachable by antibodies, with high confidence; UniProt places it where antibodies can reach, with medium confidence; UniProt predicts a signal peptide or a membrane-spanning region; the Human Protein Atlas places it where antibodies can reach. PROTAC: ubiquitination databases record sites on it.
Gene: Protein-coding gene on chromosome 19 (44,846,175 to 44,889,228, forward strand). Ensembl gene ENSG00000130202.
Subcellular location: Cell membrane
Subcellular location (Human Protein Atlas): Vesicles; Mitotic spindle; Plasma membrane
Pathways (Reactome):
Cell-Cell communication: Adherens junctions interactions; Nectin/Necl trans heterodimerization
Immune System: Immunoregulatory interactions between a Lymphoid and a non-Lymphoid cell
Gene Ontology:
Molecular function: cell adhesion molecule binding; identical protein binding; protein binding; receptor ligand activity; coreceptor activity; virus receptor activity; protein homodimerization activity
Biological process: adhesion of symbiont to host; coreceptor-mediated virion attachment to host cell; fusion of virus membrane with host plasma membrane; homophilic cell-cell adhesion; natural killer cell mediated cytotoxicity; negative regulation of natural killer cell mediated cytotoxicity; positive regulation of immunoglobulin mediated immune response; positive regulation of mast cell activation; positive regulation of natural killer cell mediated cytotoxicity; positive regulation of natural killer cell mediated cytotoxicity directed against tumor cell target; positive regulation of T cell receptor signaling pathway; regulation of viral entry into host cell; susceptibility to natural killer cell mediated cytotoxicity; susceptibility to T cell mediated cytotoxicity; spermatid development; signal transduction; symbiont entry into host cell
Cellular component: cell surface; cell-cell junction; extracellular exosome; focal adhesion; membrane; plasma membrane; apical junction complex; zonula adherens; cell-cell contact zone
Genetic constraint (gnomAD): Loss-of-function variants: 23 observed, 49.49 expected, observed/expected ratio (o/e) 0.46, 90% interval 0.33 to 0.66. The upper end of that interval is the gene's LOEUF score, 0.66, which puts it in group 2 of 6, group 1 being the genes least tolerant of losing a copy. Missense variants: 587 observed, 696.59 expected, observed/expected ratio (o/e) 0.84, 90% interval 0.79 to 0.9. Synonymous variants: 302 observed, 297.34 expected, observed/expected ratio (o/e) 1.02, 90% interval 0.92 to 1.12.
Homologues: Orthologues: chimpanzee NECTIN2 (99% identical), macaque NECTIN2 (97% identical), dog NECTIN2 (77% identical), mouse Nectin2 (74% identical), rat Nectin2 (74% identical), guinea pig NECTIN2 (71% identical), rabbit NECTIN2 (69% identical), tropical clawed frog nectin2 (30% identical), zebrafish si:ch73-22o12.1 (26% identical), zebrafish pvrl2l (22% identical), Drosophila melanogaster Fas3 (14% identical), zebrafish zgc:113337 (13% identical), and 2 more. Paralogues in human: PVR (37% identical), NECTIN1 (28% identical), NECTIN3 (24% identical), NECTIN4 (19% identical), CADM1 (16% identical), CADM3 (16% identical), CADM2 (15% identical), CADM4 (14% identical), CD226 (11% identical), CD200 (11% identical), CRTAM (10% identical), TIGIT (8% identical), and 2 more.
Diseases named in the same sentence as NECTIN2 in open-access papers:
NECTIN2 is named in the same sentence as 111 diseases in open-access papers, as found by Europe PMC text mining. Sharing a sentence is not in itself a finding about the gene and the disease. The quoted sentences say what the papers report.
melanoma (27 papers, 2013 to 2025). A malignant, usually aggressive tumor composed of atypical, neoplastic melanocytes. "Nectin-2 is overexpressed in various cancers, including breast, ovarian, melanoma, prostate, and pancreatic cancers." (PMID 36293219, 2022). "As anticipated, tumor Ca2+ influx was almost completely abolished in the Necl5−/− Nectin2−/− B16F10 cells, suggesting that damage to tumor cells is dependent on the engagement of Necl5 and/or Nectin2 on melanoma cells." (PMID 35113018, 2022). "Because the expression of Nectin2 was significantly less than that of Necl5 in B16F10 melanoma cells, we focused on Necl5." (PMID 35113018, 2022). "The analysis of large panels of melanoma cells showed that ligands for NKG2D (MICA/B, ULBPs) and DNAM-1 (PVR, Nectin-2) are widely expressed by melanoma cells." (PMID 34712615, 2021). "CD155, also known as poliovirus receptor (PVR), and poliovirus receptor-related 2, also known as CD112 or nectin-2, are expressed on a variety of tumor tissues, including leukemias, ovarian cancer, neuroblastoma, melanoma, and glioblastoma." (PMID 35011583, 2021). "Stimulation of DNAM-1 by its ligands CD155 (poliovirus receptor) and CD112 (nectin-2) expressed on different types of tumors including melanoma, leukemia, and ovarian carcinoma leads to NK cell activation and target cell lysis." (PMID 23755049, 2013). "The role of the NECTIN2-TIGIT axis in melanoma of the extremities still needs further validation." (PMID 38528036, 2024). "Both CD112 (Nectin-2), as well as CD155 (poliovirus receptor, PVR), which are widely expressed by cancer cells such as melanoma, are recognized by DNAM-1." (PMID 38057843, 2023). "The two agonists of TIGIT, CD155 (also known as poliovirus receptor [PVR]) and CD112 (alternatively termed as PVRL2 or nectin-2), are widely expressed by immune, non-immune, and tumor cells, including melanoma cells." (PMID 38617537, 2024). "Melanoma cells mainly express NKG2D and DNAM-1 ligands but not ULBPs or nectin-2, which suggests that NK cells are activated via these receptors against melanoma." (PMID 36434591, 2022). "This, together with the frequent expression on melanoma cells of ligands recognized by major activating NK receptors (including MICA/B, ULBPs, PVR, Nectin-2 and B7H6), suggests that NK cells may indeed represent important effectors against this tumor." (PMID 27563819, 2016). "Two agonists, CD155 (poliovirus receptor-PVR) and CD112 (PVRL2, nectin-2), are expressed by immune cells, non-immune cells, and by tumor cells including melanoma." (PMID 29544515, 2018). "TIGIT binds two ligands, CD112 (nectin-2, also known as PRR2 or PVRL2) and, with much higher affinity, CD155 (PVR or Necl-5), both identified on APCs, T cells and a variety of non-hematopoietic cell types including melanoma cells." (PMID 34572799, 2021).
breast carcinoma (25 papers, 2013 to 2025). "Our study has shown that high levels of Nectin-1 and Nectin-2 is associated with poor prognosis and patient outcome in human breast cancer." (PMID 24386110, 2013). "Furthermore, nectin-2 also has the potential to be a prognostic and diagnostic marker in cancers such as gallbladder cancer, pancreatic cancer, oesophageal cancer, breast cancer, and acute myeloid leukemia." (PMID 40244005, 2025). "Additionally, upregulated B2M is also associated with a poorer prognosis, and NECTIN2 is a potential target of antibody therapy for breast cancer." (PMID 38783355, 2024). "The interaction between TIGIT and NECTIN2 has been demonstrated to play a critical immune checkpoint regulatory role within the tumor immune microenvironment of breast carcinoma and neuroblastoma." (PMID 40855305, 2025). "We experimentally found that FBXW9 repressed the expression of NECTIN2, a regulator of the tumor microenvironment, in breast cancer cells." (PMID 36982338, 2023). "A more extensive IHC study indicated that Nectin-2 protein was over-expressed in more than 80% of breast cancer tissue samples and approximately 50% of ovarian cancer tissues samples." (PMID 23758976, 2013). "Furthermore, the authors of the study raised the issue of more frequent metastasis in breast cancers with higher nectin-2 expression." (PMID 40244005, 2025). "Similarly, the overexpression of nectin-2 is a worse prognostic factor (greater tumor advancement and shorter patient survival) in cancers such as gallbladder, esophagus, and breast cancer." (PMID 40244005, 2025). "Furthermore, transcriptome data suggested that NECTIN2-TIGIT-mediated interactions between metastatic breast cancer cells and tumor microenvironment (TME) cells, which promoted immune escape and lymph node metastasis." (PMID 34611125, 2021). "In breast cancer metastatic tumors have increased expression of nectin-1 and nectin-2." (PMID 30759143, 2019). "Also, Nectin-2 is highly expressed in some epithelial cancers, such as breast cancer, ovarian cancer, gallbladder cancer, and cervical cancer, and higher Nectin-2 expression was found in more malignant cancers with rapid progression and poor prognosis." (PMID 26294807, 2015). "Both receptors recognize CD155 (also known as PVR) and CD112 (also known as Nectin-2), ubiquitous cell-adhesion molecules overexpressed in HER2+ breast cancer cell lines." (PMID 29181007, 2017). "A representative anti-Nectin-2 mAb in epitope bin VII, Y-443, showed anti-tumor effects against OV-90 cells and MDA-MB-231 breast cancer cells in mouse therapeutic models, and its main mechanism of action appeared to be ADCC." (PMID 23758976, 2013). "A representative anti-Nectin-2 mAb in epitope bin VII, Y-443, showed anti-tumour effects against OV-90 cells and MDA-MB-231 breast cancer cells in mouse therapeutic models, and its main mechanism of action appeared to be ADCC." (PMID 24386110, 2013). "In a single-cell sequencing of breast cancer, NECTIN2-TIGIT mediated interactions between metastatic breast cancer cells and TME cells that promote immune escape and lymph node metastasis." (PMID 38528036, 2024). "For the evaluation of anti-Nectin-2 antibodies in in vitro assays and in vivo studies, we selected OV-90 ovarian cancer cells, which highly expressed Nectin-2 with a median fluorescent intensity (MFI) of 242 in FCM, and MDA-MB-231 breast cancer cells (MFI = 181)." (PMID 23758976, 2013).
ovarian carcinoma (23 papers, 2013 to 2024). A malignant neoplasm originating from the surface ovarian epithelium. "Knock-out of NECTIN2 using CRISPR/Cas9 inhibited ovarian cancer cell (SKOV3) proliferation, and increased T cell proliferation when co-cultured." (PMID 38278958, 2024). "High Nectin2 expression has also been reported in ovarian cancer, where it supports tumor cell adhesion, promoting tumor growth." (PMID 36916296, 2023). "Nectin-2, which is overexpressed in ovarian cancer, is a known immune checkpoint that deregulates immune cell function." (PMID 36293219, 2022). "Quantitative real time—polymerase chain reaction (qRT-PCR)—and western blot showed that nectin-2 was overexpressed in ovarian cancer cells, in agreement with a previous report." (PMID 36293219, 2022). "The level of nectin-2 was significantly increased in tumor biopsies from patients with ovarian cancer with metastases in the LN and with residual tumor > 1 cm after surgery." (PMID 35330327, 2022). "It has been reported that nectin-2 is highly expressed in ovarian and breast cancers and is significantly upregulated in ovarian cancer patients with lymph node metastasis." (PMID 36293219, 2022). "In a previous study, we reported that Nectin-2 is over-expressed in breast and ovarian cancer and is involved in cancer proliferation." (PMID 29723247, 2018). "In our previous study, we have demonstrated that Nectin-2 is over-expressed in breast and ovarian cancer tissues by using gene expression analysis and immunohistochemistry." (PMID 29723247, 2018). "In our previous study, we demonstrated that Nectin-2 is over-expressed in both breast and ovarian cancers." (PMID 29723247, 2018). "The over-expression of Nectin-2 has previously been described in breast and ovarian cancer tissues using gene arrays and immunohistochemistry." (PMID 24386110, 2013). "This study demonstrated the over-expression of Nectin-2 in breast and ovarian cancer tissues and showed that the anti-Nectin-2 human mAb Y-443 exerts an in vivo anti-tumor effect on OV-90 and MDA-MB-231 cells via ADCC as the main mechanism of action." (PMID 23758976, 2013). "We observed the over-expression of Nectin-2 in breast and ovarian cancers and anti-tumor activity of anti-Nectin-2 mAbs via strong ADCC." (PMID 23758976, 2013). "The over-expression of Nectin-2 in breast and ovarian cancer tissues and various cancer cell lines at the mRNA and protein levels suggests the potential of Nectin-2 as a target for antibody therapeutics to treat patients that are afflicted with these cancers." (PMID 23758976, 2013). "The anti-Nectin-2 poAb at 30 μg/mL inhibited the proliferation of OV-90 ovarian cancer cells by 10–15%." (PMID 23758976, 2013). "Since a partial growth inhibition of OV-90 ovarian cancer cells had been observed using anti-Nectin-2 poAb, we generated 256 Nectin-2-specific fully human mAbs from KM mice." (PMID 23758976, 2013). "In the present study, we found that Nectin-2 was over-expressed in clinical breast and ovarian cancer tissues by using gene expression profile analysis and immunohistochemistry studies." (PMID 23758976, 2013). "Anti-Nectin-2 rabbit poAb moderately suppressed the in vitro proliferation of OV-90 ovarian cancer cells." (PMID 23758976, 2013). "A single-cell interaction study on ovarian cancer reveals heterogeneous epithelial-immune-stromal cellular compartments and their interactions in shaping the tumor microenvironment, especially through the NECTIN2-TIGIT interaction." (PMID 38278958, 2024). "In addition, Oshimaet al. noted Nectin2 overexpression in breast and ovarian cancers and the antitumour activity of anti-Nectin2 mAbs." (PMID 36916296, 2023). "It was shown to be nectin-2 positive in about 48% of ovarian cancer patients." (PMID 36293219, 2022). "Therefore, we studied the feasibility of its application as an ADC in nectin-2-overexpressing ovarian cancer cells." (PMID 36293219, 2022).
ovarian carcinoma (continued). "This study observed that patients with more advanced stages of ovarian cancer displayed an overexpression of Nectin-2 in cancer cells, a lower expression of Nectin-2 in peritoneal endothelium cells, and a significantly higher concentration of circulating vascular endothelial growth factor (VEGF)." (PMID 36553083, 2022). "Expression of nectin-2 in ovarian cancer can maintain adhesion of tumor cells that leads to growth and metastasis in the LN, and VEGF-induced suppression of nectin-2 in the peritoneal endothelium can increase vascular permeability leading to the formation of ascites." (PMID 35330327, 2022). "It has been proposed that Nectin-2 is a potential target for breast and ovarian cancers." (PMID 35562985, 2022). "Taken together, these results suggested that an ADC targeting nectin-2 could be useful in the treatment of ovarian cancer, as well as other nectin-2-positive cancers, including breast, colon, and lung cancers." (PMID 36293219, 2022). "First, we examined nectin-2 expression in ovarian cancer cell lines." (PMID 36293219, 2022). "We generated numerous Nectin-2-specific fully human monoclonal antibodies (mAbs) and demonstrated the anti-tumor effect of the selected mAb clone, Y-443 (human IgG1/kappa), on breast cancer and ovarian cancer cells." (PMID 29723247, 2018). "Indeed, a previous study using a polyclonal antibody specific to Nectin-2 showed that Nectin-2 is involved in the proliferation of ovarian cancer cells." (PMID 26294807, 2015). "In the present study, we show that Nectin-2 is over-expressed in various cancers and that anti-Nectin-2 mAb can exert an in vivo anti-tumor effect on breast and ovarian cancer cells, which suggests the potential of Nectin-2 as a target for antibody therapy for cancer treatment." (PMID 23758976, 2013). "Indeed, Nectin-2 has been found to be over-expressed in clinical breast and ovarian cancer tissues by using gene expression profile analysis and immunohistochemistry studies." (PMID 24386110, 2013). "We subsequently confirmed the over-expression of Nectin-2 protein in breast and ovarian cancer tissues by immunohistochemistry (IHC) and found that Nectin-2 protein was abundantly present in these cancer tissues while it was undetectable in normal breast and ovary tissues." (PMID 23758976, 2013). "Furthermore, the polyclonal antibody specific to Nectin-2 suppressed the in vitro proliferation of OV-90 ovarian cancer cells, which express endogenous Nectin-2 on the cell surface." (PMID 23758976, 2013). "Furthermore, Nectin-2 was broadly over-expressed in various breast and ovarian cancer cell lines when its expression was tested by flow cytometry (FCM) analysis using anti-Nectin-2 poAb." (PMID 23758976, 2013). "Interestingly, a polyclonal antibody specific to Nectin-2 suppressed the in vitro proliferation of OV-90 ovarian cancer cells, which express endogenous Nectin-2 on the cell surface." (PMID 24386110, 2013). "Moreover, blockade via anti-Nectin-2 monoclonal antibodies can induce antibody-dependent cellular cytotoxicity (ADCC) with robust anti-tumor response in breast and ovarian cancers, indicating its role in immune regulation." (PMID 37256148, 2023). "c12G1-DM1 induced cell cycle arrest at the mitotic phase in nectin-2-positive ovarian cancer cells, but not in nectin-2-negative cancer cells." (PMID 36293219, 2022). "Fluorescence-activated cell sorting (FACS) analysis showed that m12G1 antibody binds to various ovarian cancer cell lines, including OV-90, SK-OV-3, and Caov-3, in a dose-dependent manner, but not to Daudi cells, which is a nectin-2-negative cell line." (PMID 36293219, 2022). "In conclusion, we developed a chimeric ADC targeting nectin-2, characterized its binding specificity, and examined its anti-tumor activity both in in vitro and in vivo models, which suggested that c12G1-DM1 is a potential therapeutic ADC that can be used to treat ovarian cancer." (PMID 36293219, 2022).